PPM1D (protein phosphatase, Mg2+/Mn2+ dependent 1D)
Description:
Mediates MAPK14 dephosphorylation and inactivation. Is also an important regulator of global heterochromatin silencing and critical in maintaining genome integrity (By similarity).
Synonyms: PP2C-delta; WIP1; IDDGIP; JDVS
Tractability: Small molecule: a high-quality ligand is known. PROTAC: ubiquitination databases record sites on it; a small molecule that binds it is known.
Target class: Protein Phosphatase; Phosphatase; Serine/threonine protein phosphatase; Enzyme
Chemical probes: GSK2830371 (high quality)
Gene: Protein-coding gene on chromosome 17 (60,599,735 to 60,666,280, forward strand). Ensembl gene ENSG00000170836.
Subcellular location: Nucleus; Cytoplasm, cytosol
Subcellular location (Human Protein Atlas): Nucleoplasm; Nucleoli
Pathways (Reactome):
Gene expression (Transcription): Transcriptional regulation by RUNX2
Gene Ontology:
Molecular function: mitogen-activated protein kinase binding; protein binding; protein serine/threonine phosphatase activity; protein serine/threonine kinase activity; cation binding
Biological process: negative regulation of gene expression, epigenetic; peptidyl-threonine dephosphorylation; DNA methylation-dependent constitutive heterochromatin formation; negative regulation of cell population proliferation; protein dephosphorylation; regulation of intracellular signal transduction; regulation of transcription initiation by RNA polymerase II; response to radiation; cellular response to starvation
Cellular component: cytosol; nucleolus; nucleoplasm; nucleus
Genetic constraint (gnomAD): Loss-of-function variants: 52 observed, 55.37 expected, observed/expected ratio (o/e) 0.94, 90% interval 0.75 to 1.18. The upper end of that interval is the gene's LOEUF score, 1.18, which puts it in group 5 of 6, group 1 being the genes least tolerant of losing a copy. Missense variants: 564 observed, 775.71 expected, observed/expected ratio (o/e) 0.73, 90% interval 0.68 to 0.78. Synonymous variants: 278 observed, 278.07 expected, observed/expected ratio (o/e) 1, 90% interval 0.91 to 1.1.
Gene-disease validity (ClinGen):
ClinGen rates the evidence that PPM1D causes each of these diseases.
syndromic intellectual disability (autosomal dominant): Definitive. A intellectual disability that is part of a larger syndrome.
Cancer hallmarks: escaping programmed cell death (promotes); proliferative signalling (promotes); genome instability and mutations (promotes)
Homologues: Orthologues: chimpanzee PPM1D (99% identical), macaque PPM1D (99% identical), dog PPM1D (94% identical), pig PPM1D (94% identical), guinea pig PPM1D (92% identical), rat Ppm1d (89% identical), mouse Ppm1d (88% identical), tropical clawed frog PPM1D (56% identical), zebrafish ppm1db (47% identical), zebrafish ppm1da (45% identical), Drosophila melanogaster Pp2C1 (34% identical), Caenorhabditis elegans ppm-1.D (29% identical). Paralogues in human: PPM1E (20% identical), PPM1B (19% identical), PPM1A (18% identical), PPM1G (16% identical), PPM1N (16% identical), PPM1F (15% identical), PDP1 (13% identical), PPM1K (13% identical), TAB1 (13% identical), PDP2 (12% identical), PPM1H (12% identical), ILKAP (12% identical), and 4 more.
Diseases named in the same sentence as PPM1D in open-access papers:
PPM1D is named in the same sentence as 148 diseases in open-access papers, as found by Europe PMC text mining. Sharing a sentence is not in itself a finding about the gene and the disease. The quoted sentences say what the papers report.
breast carcinoma (62 papers, 2008 to 2025). "Truncating mutations in PPM1D were detected in four patients (~0.3% of total cases), one (1/725, 0.14%) with breast cancer and three (3/246, 1.22%) with ovarian cancer." (PMID 31242196, 2019). "Gain-of-function mutations of PPM1D have been reported in a wide variety of cancers, including breast cancer and ovarian cancer." (PMID 31242196, 2019). "The fact that most of the somatic mosaic mutations in PPM1D were observed in the blood of patients with ovarian and breast cancer supports the association of these mutations with platinum-based chemotherapy." (PMID 31242196, 2019). "Loss of Ppm1d protected mice from development of MMTV-Erb2-driven mammary tumors, Eμ-myc-induced B-cell lymphomas and Apcmin-driven intestinal adenocarcinoma." (PMID 31659152, 2019). "WIP1 is encoded by PPM1D gene located at chromosomal locus 17q23.2 and its amplification was reported in about 10% of breast cancers." (PMID 28439615, 2017). "It has been shown that the amplification of and mutations in the PPM1D gene occurred mainly in the luminal subtype of human breast cancer." (PMID 26883196, 2016). "Loss of Ppm1d dramatically delayed the development of Erbb2-induced breast cancer, MYC-induced lymphoma and APCmin-induced intestinal tumors in mice." (PMID 26883108, 2016). "For breast cancer, ovarian cancer, lung adenocarcinoma and hepatocellular carcinoma, PPM1D overexpression is associated with poor survival." (PMID 25123458, 2014). "For breast cancer, ovarian cancer and lung adenocarcinoma, PPM1D overexpression is associated with poor survival." (PMID 23556002, 2013). "In recent studies, these truncating mutations of PPM1D in mosaic form were found in the blood with higher frequency among patients with ovarian cancer or breast cancer than in the control group, suggesting a causal relationship between the mutations and the cancers." (PMID 31242196, 2019). "Gene amplification and overexpression of PPM1D have been reported in various malignancies, including breast cancer, lung cancer, and haematological malignancies, contributing to cancer progression and metastasis." (PMID 40931354, 2025). "This is evident in our study as PPM1D alterations were the most common CH alterations among patients with ovarian cancer and the second most common CH alteration among patients with breast cancer." (PMID 40361359, 2025). "In human breast cancer tissues, PPM1D expression levels were shown to be inversely correlated with p38MAPK activity and low p16 levels." (PMID 39702569, 2024). "It has also been found that in breast cancer cell lines with reduced expression of PPM1D, there is an increase in p38MAPK activity and an increase in HBP1 protein levels, thereby inducing senescence." (PMID 39702569, 2024). "Whereas the loss of PPM1D protected mice from the development of cancer in various mouse models, PPM1D overexpression or amplification of 17q23 locus carrying the PPM1D gene have been reported in various solid tumors, including ~10% of breast cancers." (PMID 37709843, 2023). "Of these genes, only RPS6KB1, VMP1, PPM1D and BCAS3 have been implicated in tumor development using clinical data from breast cancer patients." (PMID 34797887, 2021).
breast carcinoma (continued). "High DNA copy-number amplification or overexpression of PPM1D has been detected in several tumors including breast cancer, ovarian cancer, and medulloblastoma." (PMID 28852847, 2017). "Both SPI-001 and SL-176 suppressed the cell proliferation in human breast cancer MCF7 cells with overexpressed wild-type PPM1D in a dose-dependent manner." (PMID 28439615, 2017). "Chromosomal locus 17q23 carrying the PPM1D (coding for WIP1) is commonly amplified in breast carcinomas and WIP1 was proposed as potential pharmacological target." (PMID 26883108, 2016). "PPM1D has been reported to be upregulated in neuroblastoma, as well as pancreatic, lung, bladder, liver, ovarian and breast cancer." (PMID 25009596, 2014). "To date, there is accumulating evidence that PPM1D is involved in multiple human tumors, including neuroblastoma, pancreatic adenocarcinoma, medulloblastoma, breast cancer, ovarian cancer and hepatocellular carcinoma, and is a promising therapeutic target." (PMID 25123458, 2014). "Protein phosphatase magnesium-dependent 1δ (PPM1D) is an oncogene, overexpressed in many solid tumors, including ovarian cancer and breast cancer." (PMID 23556002, 2013). "ON-TARGETplus siRNAs for a top hit, PPM1D, were transfected in two breast cancer cell lines, MCF-7 and MDA-MB-468." (PMID 20576088, 2010). "Genes such as NCOA3, PPM1D, PSMD6 and BCAS2 were detected with high expression and copy numbers in MCF-7 cells, and these genes have been associated with breast cancer progression." (PMID 18350142, 2008). "PIK3CA (5290) and PPM1D (8493) are two breast cancer gene markers in the GSE1561 dataset." (PMID 34573857, 2021). "We examined the expression of PPM1D mRNA in a panel of cell lines, including both neuroblastoma and medulloblastoma, as well as the breast cancer cell lines MCF-7 and BT-474 exhibiting PPM1D gene amplification, and one sPNET cell line (PSFK-1) containing isochromosome 17." (PMID 34885154, 2021). "About one third of breast tumors with PPM1D overexpression showed also amplification of ERBB2 suggesting that these two oncogenes may cooperatively promote breast cancer development." (PMID 28439615, 2017). "PPM1D amplification and overexpression have been demonstrated in multiple human tumors, including neuroblastoma, pancreatic adenocarcinoma, medulloblastoma, breast cancer and ovarian clear cell carcinoma." (PMID 25123458, 2014). "PPM1D amplification is found in several solid tumors, including medulloblastoma, neuroblastoma, pancreatic adenocarcinoma, ovarian clear cell carcinoma and breast cancer." (PMID 23556002, 2013).
breast carcinoma (continued). "Only two of the CNA events identified in MPA/DMBA-induced tumors occur at a notable rate in human breast cancer; MDM4 is amplified in 25%, and PPM1D is amplified in 10% of human BC." (PMID 31366361, 2019). "In contrast to Torii’s study, Ak’s group explored the breast cancer cell line MCF7, demonstrating PPM1D overexpression." (PMID 39702569, 2024). "All neuroblastomas expressed PPM1D mRNA, and the highest expression was observed in SK-N-DZ and IMR32, showing expression levels comparable to the PPM1D-amplified breast cancer cell lines MCF-7 and BT-474." (PMID 34885154, 2021). "When the chemical inhibitors CCT007093 (PPM1D inhibitor) and mithramycin (SP1-binding inhibitor) were used in combination with paclitaxel, we observed synergistic growth inhibition of breast cancer cell cultures." (PMID 23281588, 2012). "PPM1D is amplified and overexpressed in breast cancers and inhibition of its activity, through use of small molecules such as CCT007093, inhibits the growth of tumor cell lines that overexpress PPM1D." (PMID 20576088, 2010). "This subset included known breast cancer genes, like EGFR (7p11), FGFR1 (8p12), ERBB2 (17q12), PPM1D (17q23) and ZNF217 (20q13)." (PMID 19582160, 2009). "To ascertain if this effect was specifically limited to DIPG and astrocyte models, we validated our results in the osteosarcoma cell line, U2OS (R458fs), as well as the breast cancer cell line MCF7 (PPM1D amplification), both which contain endogenous PPM1D alterations." (PMID 31439867, 2019). "The demonstration that Ppm1d-deficient mice significantly delayed the formation of ERBB2-induced mammary tumors and that Ppm1d-null embryonic mouse fibroblasts were resistant to transformation by RAS, ERBB2, and c-MYC encouraged us to establish a genetically modified mouse model overexpressing WIP1." (PMID 34771656, 2021). "In the same time, however, MMTV-driven overexpression of PPM1D in mice did not promote mammary tumor formation within 2 years suggesting that oncogenic properties of WIP1 may be relatively low." (PMID 28439615, 2017). "For instance, mice lacking the Wip1 phosphatase (also known as PPM1D; protein phosphatase magnesium-dependent 1D) have a delay in HER2/neu (human epidermal growth factor 2), but not Wnt1-induced mammary tumor formation." (PMID 23369183, 2013).
glioma (26 papers, 2008 to 2025). A benign or malignant brain and spinal cord tumor that arises from glial cells (astrocytes, oligodendrocytes, ependymal cells). "Ppm1d mutations affected tumor cell proliferation and developmental cell state in these mouse gliomas." (PMID 41394550, 2025). "Here we developed a mouse allele to conditionally express a glioma-derived oncogenic Ppm1d mutation from the endogenous mouse Ppm1d locus." (PMID 41394550, 2025). "Gain-of-function mutations in PPM1D leading to expression of a stable PPM1D protein have been implicated in solid tumors (including breast, colon cancer, and glioma) and in age-related or therapy-induced clonal hematopoiesis." (PMID 37709843, 2023). "Previous work in gliomas has largely focused on the role of PPM1D mutation as a driver of radiation resistance and/or evaluated therapeutic vulnerabilities associated with the mutation." (PMID 35105861, 2022). "Among 41 pediatric cancers encompassing 13 histological subtypes, we found PPM1D truncating mutations in only 0.2% of all tumors, with gliomas being the top tumor type (1.37%)." (PMID 35105861, 2022). "PPM1D mutations have previously been reported in gliomas and have been shown to confer resistance to radiation." (PMID 35105861, 2022). "Amplification of the 17q locus containing PPM1D/ WIP1 and gain of function mutations occur in multiple pediatric tumors including gliomas, medulloblastomas, and neuroblastomas." (PMID 25658463, 2015). "PPM1D silencing has been found to be associated with tumor sensitivity to treatment in gliomas." (PMID 37360159, 2023). "We, therefore, reasoned that PPM1D truncations associated with PPM1D-mutant gliomas may also exhibit the enhanced activity of the PPM1D phosphatase, targeting known substrates in the DDR and cell cycle pathways." (PMID 35105861, 2022). "In addition to the most common glioma mutations, others were detected as PPM1D mutation (3 out 10 tested samples), PIK3CA mutation (2/10 tested), BCOR mutation (1/10 tested) and SETD2 mutation in 1/10 test SCA." (PMID 35267601, 2022). "Here we analyze whole genome sequences of 170 pediatric high-grade gliomas and find that truncating mutations in PPM1D that increase the stability of its phosphatase are clonal driver events in 11% of Diffuse Midline Gliomas (DMGs) and are enriched in primary pontine tumors." (PMID 35105861, 2022). "In contrast, PPM1D mutations appear to occur predominantly in gliomas in children." (PMID 35105861, 2022). "In keeping with this notion, mutations in the protein phosphatase Mg2+/Mn2+-dependent 1D (PPM1D) gene in pediatric gliomas also drive NAPRT gene silencing through the hypermethylation of CpG islands in the NAPRT promoter, thus, again conferring unique sensitivity to NAMPT inhibitors." (PMID 34068917, 2021). "After filtering, 10,461 cells were examined from primary glioma-bearing brains derived from Ppm1d-flex-6 or matched littermate Ppm1d-wt mice." (PMID 41394550, 2025). "We next explored effects of mutant Ppm1d on the transcriptional cell state of primary mouse gliomas using single cell RNA-seq." (PMID 41394550, 2025).